PAX6 (paired box 6)
Diseases named in the same sentence as PAX6 in open-access papers (continued):
Sharing a sentence is not in itself a finding about the gene and the disease.
Obesity (13 papers, 2015 to 2024). Accumulation of substantial excess body fat. "db/db mice represent a model of T2D with obesity that develops beta cell failure, characterized by severe hyperglycemia, beta cell dysfunction, loss of beta cell identity, and PAX6 down‐regulation in islets." (PMID 37933577, 2023). "Systemically, isolated PAX6 mutations have been associated with reports of type 1 and 2 diabetes, obesity, brain anatomical and neurodevelopmental anomalies, neurobehavioral disorders, and autism spectrum disorder." (PMID 34101622, 2021). "Defects in PAX6 have also been associated with obesity and diabetes mellitus due to its role in pancreas development." (PMID 31861090, 2019). "Genetically, segmental deletions encompassing the WT1 and PAX6 genes are known to cause the syndromic phenotype, while an accompanying phenotype of obesity is linked to the extensive deletion involving the brain-derived neurotrophic factor (BDNF) locus." (PMID 29061165, 2017). "While the role of BDNF deletion in obesity and other metabolic characteristics has been explored, it is also possible that the PAX6 deletion may contribute to some of the metabolic abnormalities that can affect patients with WAGR Spectrum." (PMID 34970513, 2021). "This further included 10 identical annotations among the PAX6 and HOXA9‐10 gene clusters, already known candidates regarding obesity and related comorbidities." (PMID 35692099, 2022). "Obesity decreases the GLP-1 cell lineage as evidenced by lower NKX2.2, PAX6, FOXA1, and PDX1 gene expression in (Ob + ObD) individuals compared to NOb individuals." (PMID 33037328, 2021). "Interestingly, obesity with T2D decreased GCG expression and its transcriptional regulator PAX6." (PMID 33037328, 2021). "In addition, despite our study being sufficiently powered, we failed to confirm the association with obesity for three novel identified adult BMI loci from East ancestry (KCNQ1-rs2237892, PAX6-rs652722 and GP2-rs12597579) in Chinese children." (PMID 29212175, 2017).
developmental delay (10 papers, 2009 to 2025). "The frequent occurrence of developmental delay in patients with PAX6 mutation argues for a prompt diagnosis of the disease." (PMID 19898691, 2009). "In our cohort, 80% (4/5) of patients with the PAX6 mutation had developmental delay." (PMID 19898691, 2009). "In the Human PAX6 Allelic Variant Database, one of the three cases with S119R mutation had a learning disability and behavioral change; one of the 20 cases with c.1267dupT mutation was recorded to have developmental delay and autistic behavior." (PMID 19898691, 2009). "Among the four patients with large deletions encompassing the entire WT1 gene, one did not have AN as their deletion did not encompass the PAX6 gene and one female patient had only AN and no GU abnormalities, with four having developmental delay." (PMID 34608521, 2022).
maturity onset diabetes (10 papers, 2011 to 2026). "In this study, we discovered the pathogenic role of Smad3 in type 2 diabetes beta cell loss and dysfunction via the Pax6-dependent mechanism." (PMID 33456576, 2021). "Additionally, isolated PAX6 mutations have been reported to be associated with type 1 and type 2 diabetes." (PMID 36202929, 2023). "Thus, transcriptional inhibition of the Pax6 in beta cells may represent as one of the key pathogenic mechanism for the Smad3-driven beta cell loss and dysfunction in type 2 diabetes." (PMID 33456576, 2021). "In conclusion, we have identified an atypical likely pathogenic missense mutation in the eye and islet transcription factor PAX6 in a family with dominant adult-onset diabetes without overt eye defects." (PMID 36202929, 2023). "We also sought to determine the importance of Pax6 in maintaining intercellular communication within the islet, a feature required for normal secretory responses to secretagogues that becomes defective in type 2 diabetes." (PMID 28377501, 2017). "Module 84 contained three effector genes from the Type 2 Diabetes Knowledge Portal—ABCC8, SLC30A8, and G6PC2—and module 103 included two effector genes: PAX6 and STARD10." (PMID 37333221, 2023).
non-small cell lung carcinoma (10 papers, 2014 to 2025). A group of at least three distinct histological types of lung cancer, including non-small cell squamous cell carcinoma, adenocarcinoma, and large cell carcinoma. "For instance, in epithelial-derived tumors such as non-small-cell lung cancer, PAX6 is overexpressed and promotes tumor proliferation." (PMID 41154694, 2025). "In contrast, PAX6 is overexpressed in non-small-cell lung cancer, where it mediates tumor cell proliferation, invasion, and cell cycle progression through the ERK and MAPK signaling pathways." (PMID 41154694, 2025). "This study investigated the function of SMAD3 (SMAD family member 3) in regulating PAX6 (paired box 6) in non-small cell lung cancer." (PMID 30594196, 2018). "SMAD3 promotes the progression of non-small cell lung cancer by upregulating PAX6 expression." (PMID 30594196, 2018). "Finally, the hypermethylation of PAX6 was observed to correlate with poor clinical outcome in gastric cancer, development of non-small cell lung cancer and transcriptional deactivation in invasive ductal breast carcinoma." (PMID 26039411, 2015). "In this study, we investigated the function of SMAD3 in non-small cell lung cancer using cell proliferation and migration experiments and explored the relationship between SMAD3 and PAX6 with double luciferase reporter experiments and chromatin immunoprecipitation assay (ChIP)." (PMID 30594196, 2018).
epilepsy (9 papers, 2007 to 2022). A brain disorder characterized by episodes of abnormally increased neuronal discharge resulting in transient episodes of sensory or motor neurological dysfunction, or psychic dysfunction. "Epilepsy has also been reported in a study of patients affected by all types of PAX6 mutations." (PMID 17417613, 2007). "In some cases, missense mutations in PAX6 have also been associated with neurodevelopmental abnormalities such as absence/hypoplasia of the anterior commissure, callosal area, or pineal gland; olfactory system anomalies; cerebellar coordination problems; mental retardation; and epilepsy." (PMID 18776953, 2008). "Using immunohistochemistry, we also studied PAX6 expression in the adult brain tissue of healthy subjects (n = 4) and patients with epilepsy (n = 42), some of whom had focal injuries due to intracranial electrode track placement (n = 17)." (PMID 27231702, 2016). "We demonstrate the use of our algorithm to predict novel candidate genes for human atrial fibrillation (such as HRH2, ATP4A, ATP4B, and HOPX) and epilepsy (e.g., PAX6 and NKX2-1)." (PMID 23800157, 2013). "It is noteworthy that RA-signalling promotes the expression of PAX6, which is a candidate gene for epilepsy and whose expression on neuronal cells may be altered by Valproate." (PMID 26011637, 2015). "PAX6/GFAP double‐labeled cells were numerous in the superficial cortex, white matter, and deeper cortex in all epilepsy cases." (PMID 27231702, 2016).
Gillespie syndrome (9 papers, 2009 to 2024). "The PAX6 gene mutations were identified in only two individuals described as Gillespie syndrome but with atypical features like corectopia and ptosis." (PMID 29460221, 2018). "PAX6 mutations have been reported in two individuals described as Gillespie syndrome but with significantly atypical features such as corectopia and ptosis." (PMID 27124303, 2016). "Later, a chromosomal deletion encompassing the 3’ regulatory region of PAX6 was also identified in a patient that was diagnosed with Gillespie syndrome." (PMID 31861090, 2019). "However, a T>A substitution in intron 2 of PAX6 was identified in two individuals that were described with Gillespie syndrome, but with atypical features, like corectopia and ptosis." (PMID 31861090, 2019). "Until now the molecular basis of Gillespie syndrome was not known, with causative mutations in PAX6, FOXC1, and PITX2 having been excluded in many reported cases." (PMID 27108798, 2016). "Analysis of the PAX6 gene in six Gillespie syndrome patients revealed no intragenic mutations." (PMID 27124303, 2016). "The eye in Gillespie syndrome can be further distinguished from PAX6-related disease by the absence of foveal hypoplasia and corneal opacification." (PMID 27108798, 2016).
neuroblastoma (9 papers, 2011 to 2022). Neuroblastoma (NB) is the most common solid, extracranial childhood tumor. "Previous studies showed that Paupar interacts with Pax6 to maintain the self-renewal of mouse neuroblastoma Neuro-2a cells." (PMID 33544864, 2021). "Moreover, PAX6 has been shown to be involved in NGN2 regulation, and NGN2 expression is repressed in Pax6(-/-) murine neuroblastoma cells." (PMID 34855047, 2022). "Treatment of N2A cells with BMP4, a component of the Bmp pathway that is known to cross-talk with Wnt signalling in neuroblastoma, led to a 2.3-fold increase in Tcf7l2 and a subsequent 2.1- and 1.9-fold up-regulation in Paupar and Pax6 expression 72 hours later." (PMID 35709096, 2022). "It was first identified in neuroblastoma modulating Paired Box 6 (PAX6) activity." (PMID 34439196, 2021). "To complement and compare with this strategy we have here used a different, unbiased approach to analyse the chromatin at the mouse Pax6 locus in three murine cell lines of different origins, MV+, a lens epithelium derived cell line, N2A, neuroblastoma, and RAG, kidney carcinoma." (PMID 22220192, 2011). "Mouse neuro 2A (N2A) neuroblastoma cells express both Paupar (at an average level of approximately 15 copies per cell) and Pax6, but not Pax6OS1, and are widely used as an in vitro model of neuronal differentiation." (PMID 24488179, 2014). "We therefore investigated Paupar-Pax6 expression control in the neuronal lineage using the following cell types: primary neural stem cells (NSCs) isolated from E14.5 mice, differentiated mouse cortical neurons, N2A mouse neuroblastoma cells, as well as mouse ESCs as a non-neuronal reference." (PMID 35709096, 2022). "Finally, treatment of N2A cells with RSPO2, a leucine rich repeat-containing G-protein coupled receptor (LGR) ligand that has been shown to amplify Wnt signal in a subset of neuroblastoma cells, did not induce significant changes in either Tcf7L2, Paupar or Pax6." (PMID 35709096, 2022).
pancreatic cancer (9 papers, 2014 to 2024). "In this study, it was found that PAX6 was negatively associated with the survival of patients with GC, indicating an oncogenic role of PAX6 in GC, which is consistent with the previously reported role of PAX6 in lung adenocarcinoma and pancreatic cancer." (PMID 34459131, 2021). "In pancreatic carcinoma, both the canonical PAX6 isoform (a) and isoform (b) (also known as 5a) are expressed and promote the expression of MET, which has been linked to pancreatic cancer progression." (PMID 38473380, 2024). "For example, silencing circFOXK2 significantly inhibited pancreatic cancer progression and elevated miR-942 expression, eventually indirectly suppressed expression of PAX6 and GDNF." (PMID 34906151, 2021). "PAX6 is also a regulator of MET tyrosine kinase receptor expression in pancreatic carcinoma cell lines." (PMID 24454925, 2014). "In pancreatic carcinoma cell lines, the inhibition of PAX6 expression leads to a decrease in cell growth and survival." (PMID 24454925, 2014). "A recent study showed that PAX6 promotes cell growth by activating the MET tyrosine kinase receptor gene in pancreatic carcinoma." (PMID 24454925, 2014).
prostate carcinoma (9 papers, 2009 to 2025). A carcinoma that arises from epithelial cells of the prostate gland. "While most Pax family members are associated with an unfavorable outcome of the cancer, Pax6 has been proposed to have a tumor suppressor function in both glioblastoma and prostate cancer." (PMID 21935435, 2011). "Importantly, loss of AR resulted in an enhanced expression of PAX6, which reprogramed the lineage plasticity of prostate cancer cells to develop NE phenotypes through the MET/STAT5A signaling pathway." (PMID 38745318, 2024). "As a comparison we investigated PAX gene expression in the melanoma cell line UACC62 which had only PAX8 expression (0.04-fold), and the prostate cancer cell line PC-3 which expressed PAX6 at 5-fold and PAX5 and PAX8 at the same level as housekeepers (1-fold)." (PMID 34722257, 2021). "In prostate cancer, PAX6 expression was lower in cancer tissues and cancer cell lines than normal epithelial cells." (PMID 24454925, 2014). "Recent reports show Pax6 to be a repressor of AR activity, and the PAX6 gene to be hypermethylated in prostate cancer cells." (PMID 21935435, 2011). "The transcription factor Pax6 has recently been reported to act as a repressor of AR and to be hypermethylated in prostate cancer cells." (PMID 21935435, 2011). "Using p285PB-Luc as a reporter, we confirm that Pax6 represses AR-mediated transactivation in LNCaP prostate cancer cells." (PMID 21935435, 2011). "Recently, we showed that the ectopic overexpression of E2F1 and Pax6 positively upregulates δ-catenin expression in prostate cancer cells." (PMID 19284555, 2009). "Overexpression of PAX6 suppressed the proliferation and colony formation of prostate cancer cells." (PMID 24454925, 2014). "Furthermore, our data show that Pax6 and AR are coexpressed in the androgen insensitive prostate cancer cell line PC3, the lens epithelial cell line B3, in addition to the cancer cell lines HEK293 and HeLa." (PMID 21935435, 2011). "In summary, Pax6, SPBP and AR are coexpressed in the B3 lens epithelial and PC3 prostate cancer cell lines." (PMID 21935435, 2011). "Recently, Pax6 and E2F1 were identified as positive transcriptional regulators for δ-catenin in the central nervous system and in prostate cancer cells." (PMID 21106062, 2010).
colorectal cancer (8 papers, 2010 to 2024). A primary or metastatic malignant neoplasm that affects the colon or rectum. "In colorectal cancer, miR-7 down-regulates the expression of paired box 6 (PAX6), which limits the PI3K/ERK-dependent up-regulation of MMP2 and MMP9 and hence inhibits colorectal cancer cell growth, proliferation, and metastasis." (PMID 36555120, 2022). "Consistent with this idea is the fact that PAX6 frameshift mutations originating at codon 375 and/or codon 376 are also recurrent in MSI-stomach cancer and MSI-colorectal carcinoma." (PMID 35081118, 2022). "We used RT-qPCR to determine the relative expression levels of four paired box (PAX) genes which are most likely to encode binding targets for EG1 in colorectal carcinoma cells (PAX2, PAX5, PAX6, PAX8)." (PMID 34722257, 2021). "PAX6 is a highly conserved transcription factor that is expressed in colorectal cancer cells and plays an important regulatory role in the development of colorectal cancer." (PMID 26516313, 2015). "By contrast, miR-7 reduces PAX6 expression in colorectal cancer cell lines and inhibits the corresponding signaling through the ERK/PI3K pathway, resulting in downregulated growth, proliferation, and metastasis of these cells significantly." (PMID 26516313, 2015). "Furthermore, differing levels of PAX6 have been shown to regulate cell cycle progression in colorectal cancer cells with high levels leading to an increase in cell proliferation through the modulation of PI3K/AKT signalling." (PMID 34722257, 2021). "Elevated expression levels of PAX6, BCL11B, MCOLN2, CUX1 and EMX1 reported in colorectal cancer positively correlate with TRPA1 in other malignancies, with a possible implication in tumorigenesis." (PMID 39770499, 2024).
Peters anomaly (8 papers, 2005 to 2025). Peters anomaly (PA) is a congenital corneal opacity disorder characterized by a central corneal leukoma that obstructs the pupil leading to visual loss as well as absence of the posterior corneal stroma and Descemet membrane. "Mice homozygous for an inactivating mutation of Pax6, a candidate for human Peter's anomaly, lack eyes." (PMID 16403239, 2005).
Cognitive impairment (7 papers, 2007 to 2024). Abnormal cognition is characterized by deficits in thinking, reasoning, or remembering. "In our research, it was also found that tooth loss leads to increased expression of Pax6, which leads to cognitive impairment in rats." (PMID 35573291, 2022). "A subset of patients affected by PAX6 mutations and presenting with agenesis of the anterior commissure was shown to have mild cognitive impairments." (PMID 17417613, 2007). "Human subjects with PAX6 mutations showed various psychiatric and cognitive disorders." (PMID 27355350, 2016). "Impairment of PAX6 activity will obviously affect the expression patterns of its target genes, and there is substantial evidence of associations between PAX6 mutations, brain development abnormalities, cognition disorders, as well as pancreatic endocrine disorders." (PMID 17417613, 2007). "Breaking this loop by upregulating IDH3β or downregulating PAX6 attenuates AD neurodegeneration and cognitive impairments." (PMID 38679634, 2024).
Corneal opacity (7 papers, 2010 to 2025). A reduction of corneal clarity. "FOSL2 is regarded as a downstream gene regulated by PAX6 and has been closely linked to corneal opacity." (PMID 40828815, 2025). "Fos like 2 (FOSL2) is considered a target gene of PAX6 and is closely associated with corneal opacity." (PMID 40828815, 2025). "As several key TFs defining the LSC fate, either shared or cell type specific, such as p63 and PAX6, respectively, are associated with corneal opacity, we explored the potential involvement of LSC TFs in the pathomechanism of corneal diseases." (PMID 37856539, 2023). "Importantly, we discovered that FOSL2, a direct PAX6 target gene, is a novel candidate associated with corneal opacity, and it regulates genes implicated in corneal diseases." (PMID 37856539, 2023). "How TFs like PAX6, p63, and FOXC1 regulate their target genes in LSCs and how their mutations give rise to LSCD and corneal opacities are not yet fully understood." (PMID 37856539, 2023). "Because PAX6 is an undisputed regulator in LSCs and defects are associated with LSCD and corneal opacity, we also performed PAX6 knockdown (siPAX6)." (PMID 37856539, 2023). "PAX6, FOXC1, and p63 are known to be associated with corneal opacity, and FOSL2 is a novel corneal opacity gene identified in this study." (PMID 37856539, 2023). "Enforced expression of PAX6 protein in the corneal endothelium led to less corneal opacity and edema via increasing the “barrier” function of CECs, thus indicating the protective potentials of PAX6." (PMID 32826860, 2020).
foveal hypoplasia (7 papers, 2014 to 2025). Underdevelopment of the fovea centralis. "According to previous reports, PAX6-associated foveal hypoplasia (FH) could usually be accompanied by various anterior segment anomalies including variable iris changes." (PMID 37553561, 2023). "The autosomal dominant form of the isolated foveal hypoplasia (FVH1, OMIM 136520) is known to be associated with hypomorphic mutations of the PAX6 gene." (PMID 37510387, 2023). "Molecular analysis showed point mutations in TYR in all patients analyzed, and none of them presented sequence alterations or copy number variants (CNVs) in PAX6, SLC38A8 or in other genes associated with foveal hypoplasia." (PMID 35887175, 2022).